MYOCD (myocardin)
Diseases named in the same sentence as MYOCD in open-access papers (continued):
Sharing a sentence is not in itself a finding about the gene and the disease.
cardiomyopathy (2 papers, 2023 to 2024). A disease of the heart muscle or myocardium proper. "All these suggest that ARP5 plays an inhibitory role in cardiac development and that increased ARP5 in the human heart may contribute to cardiomyopathy and associated cardiac fibrosis through suppression of cardiac MYOCD function." (PMID 36610028, 2023). "Myocardin expression was decreased in Atp6v0d1AKO cardiomyopathy, and mimicking myocardin downregulation in cardiomyocytes decreased ANP expression." (PMID 38505620, 2024). "Given the critical role of disturbed cardiac metabolism in the development of cardiomyopathy, we decided to investigate the contribution of myocardin downregulation to metabolic disorders in Atp6v0d1AKO mouse hearts." (PMID 38505620, 2024). "Interestingly, myocardin upregulation largely restored the expression of the genes controlling FA uptake and oxidation, and glucose metabolism, suggesting a critical role for myocardin in causing lipid and glucose metabolism disorder in Atp6v0d1AKO cardiomyopathy." (PMID 38505620, 2024). "Taken together, we propose that the myocardin inhibition-insulin resistance-increased FoxO1 expression signaling axis plays a central role in promoting lipid and glucose metabolism disorder and the development of cardiomyopathy in Atp6v0d1AKO mice." (PMID 38505620, 2024). "Our findings suggest that decreased myocardin expression may explain the distinct HF phenotype in obesity cardiomyopathy." (PMID 38505620, 2024).
congenital megabladder (2 papers, 2022 to 2025). "Along these lines, mutations in MYOCD cause congenital megabladder and associated cardiovascular phenotypes such as PTA and VSD in humans, but monoallelic mutations affect only males whereas biallelic mutations affect both sexes." (PMID 35044299, 2022).
embryonic carcinoma (2 papers, 2019 to 2023). "More specifically, knockdown of mm-85 derived lncRNA in P19CL6 mouse embryonic carcinoma cells significantly decreased myocardin expression and upregulated mm-67 present within the myocardin gene." (PMID 31681761, 2019). "This shows the crucial role of mm-85 in regulating myocardin expression in mouse P19CL6 embryonic carcinoma cells." (PMID 31681761, 2019). "We examined the role of ARP5 in MYOCD–SRF and MEF2C function using the murine p19 embryonic carcinoma P19CL6 cell line." (PMID 36610028, 2023).
idiopathic pulmonary fibrosis (2 papers, 2018 to 2023). Idiopathic pulmonary fibrosis (IPF) is a nonneoplastic pulmonary disease that is characterized by the formation of scar tissue within the lungs in the absence of any known cause. "Snitow reported that EZH2 loss reduces the expression of myocardin and TBX18, thereby affecting the autonomic inhibition of smooth muscle differentiation in mesothelium cells, and ultimately contributing to the development of COPD and idiopathic pulmonary fibrosis." (PMID 38114929, 2023).
infarction (2 papers, 2016 to 2025). A localised pathological necrosis of tissue resulting from obstruction of the blood supply usually by a thrombus, an embolus, or vascular torsion. "Some experiments have also indicated that umbilical cord MSCs, characterized by elevated expression of GATA4 and myocardin (MYOCD), can effectively reduce post-infarction cardiomyocytes apoptosis." (PMID 40649781, 2025). "It has also been found that the hypoxic environment of infarction may induce the expression of certain factors (vascular endothelial growth factor, myocardin, insulin like growth factor) which can promote the differentiation of MSCs to cardiomyocytes." (PMID 27539581, 2016).
liver fibrosis (2 papers, 2012 to 2018). "The myocardin pathway is therefore a promising new therapeutic target in the treatment of liver fibrosis." (PMID 23259668, 2012). "Further cellular localization studies will help to understand the function of myocardin in liver fibrosis." (PMID 23259668, 2012). "Thus, myocardin may play a key role in fibroblast trans-differentiation into myofibroblast-like cells during liver fibrosis." (PMID 23259668, 2012).
Obesity (2 papers, 2023 to 2024). Accumulation of substantial excess body fat. "The therapeutic effect of myocardin on treatment of diabetic and obesity cardiomyocytes, as well as the mechanism underlying systemic insulin resistance and reduction of myocardin in heart warrants future study." (PMID 38505620, 2024).
osteosarcoma (2 papers, 2012 to 2024). A usually aggressive malignant bone-forming mesenchymal neoplasm, predominantly affecting adolescents and young adults. "For example, MIR145 mediates myocardin gene upregulation during muscle differentiation, while the same miRNA induces ROCK1 downregulation in osteosarcoma." (PMID 38413914, 2024).
prostate carcinoma (2 papers, 2015 to 2023). A carcinoma that arises from epithelial cells of the prostate gland. "A dual requirement of SRF and myocardin for regulation of PTRF, but not for regulation of CAV1, suggests a mechanism for uncoupling of PTRF synthesis from CAV1 synthesis, such as seen in prostate cancer cells." (PMID 26244347, 2015).
thoracic aortic aneurysm (2 papers, 2017 to 2023). An aneurysm formed in the wall of the proximal portion of the descending aorta proceeding from the arch of the aorta. "Mutations in target genes of myocardin, including Myh11, Acta2, and Mylk, are known causes of thoracic aortic aneurysms with dissection (TAAD), but most studies show a limited genetic overlap between AAAs and TAAs." (PMID 37561588, 2023). "We measured the expression level of MYOCD gene encoding myocardin in smooth muscle cells (SMC) derived from aortic wall of the patients with thoracic aortic aneurysm (TAA) associated with either tricuspid- or bicuspid aortic valve (TAV- and BAV- correspondingly) and healthy controls." (PMID 28790933, 2017). "In this study we show that smooth muscle cell differentiation pathways that are dependent on myocardin and TGF-β are attenuated in the patients with thoracic aortic aneurysm associated with bicuspid or tricuspid aortic valve." (PMID 28790933, 2017).
adenovirus infection (1 paper, 2012). "It should be noted that adenovirus infection by itself resulted in a small increase in SMA+ and SMMHC+ cells although there was always a clear effect of myocardin over the virally delivered LacZ negative control." (PMID 22937150, 2012).
Aortic root aneurysm (1 paper, 2020). An abnormal localized widening (dilatation) of the aortic root. "RT‐PCR of our MFS aortic root aneurysm tissue (tunica media) demonstrated a 2.4‐fold increased expression of myocardin (MYOCD) relative to non‐dilated donor control aortic roots (n = 6, P = .015)." (PMID 31886938, 2020).
arterial diseases (1 paper, 2016). "In fact, many YAP targets, including transcriptional coactivator with PDZ-binding motif (TAZ), TEAD family transcription factors, and the myocardin-SRF complex, have been studied in the context of other arterial diseases." (PMID 27608489, 2016).
Atherosclerotic lesion (1 paper, 2023). A lesion associated with atherosclerosis, a multifactorial and multipart progressive disease manifested by the focal development within the arterial wall of lesions, that ranges from the development of a fatty streak, plaque progression, and plaque disruption. "MYOCD and SRF complex increases expression of VSMC differentiation markers by binding the CArG box of target promoters to form a MYOCD-SRF-CArG box complex, overexpression of MYOCD up-regulates the expression of multiple contractile genes and prevents atherosclerotic lesions." (PMID 36604627, 2023).
Brugada syndrome (1 paper, 2022). A genetically heterogeneous condition characterized by complete or incomplete right bundle branch block accompanied by ST elevation in leads V1-V3. "For example, SRF、MYOCD are related to the development of cardiac vascular smooth muscle and molecular regulation of diseases, Mutations in HEY2 cause Brugada syndrome, a rare heart disease." (PMID 36303246, 2022).
cerebral aneurysm (1 paper, 2023). "TNFα can also induce cerebral SMC phenotypic changes through KLF4 and Myocardin, which may contribute to cerebral aneurysm formation." (PMID 37686377, 2023).
chronic kidney disease (1 paper, 2022). Impairment of the renal function secondary to chronic kidney damage persisting for three or more months. "In addition, myocardin levels are drastically decreased after ferric citrate treatment, and ferric citrate is administered to patients with chronic kidney disease (CKD) postdialysis to regulate blood iron levels." (PMID 35681202, 2022).
congenital heart disease (1 paper, 2023). A heart disease that is present at birth. "Furthermore, K259R mutation of MYOCD, which creates a hypomorphic cardiac MYOCD with impaired transactivation capacity, has been reported in patient with congenital heart disease." (PMID 36610028, 2023).
congenital muscular dystrophy (1 paper, 2025). A muscular dystrophy that is characterized by diminished muscle tone (hypotonia), progressive muscle weakness and degeneration (atrophy), abnormally fixed joints, spinal rigidity, and delays in reaching motor milestones such as sitting or standing unassisted. "MYOCD is associated with muscular atrophy, whereas LARGE1 is related to congenital muscular dystrophy." (PMID 40600194, 2025).
diabetic cardiomyopathy (1 paper, 2024). Diabetic cardiomyopathy is a disorder of the heart muscle in people with diabetes. "Myocardin expression was also reduced in high fat diet-induced diabetic cardiomyopathy and palmitic acid-treated cardiomyocytes." (PMID 38505620, 2024).
endometriosis (1 paper, 2021). The growth of functional endometrial tissue in anatomic sites outside the uterine body. "In addition, some identified hub genes of the EC (TAGLN, GATA6, CDH3, CLU, COL8A1, MYH11, MYOCD) and EU (CXCL13, DDK-1, KLF4, CYP2E1, CYP4B1 and PROK1) have been reported be associated with endometriosis." (PMID 34522169, 2021).
erectile dysfunction (1 paper, 2019). Persistent or recurrent inability to achieve or to maintain an erection during sexual activity. "This study aims to prove the myocardin genetic modification of ASCs to improve erectile dysfunction in diabetic rats." (PMID 31311594, 2019). "In the current research, there were two possibilities in the contribution of myocardin to the improvement of erectile dysfunction in diabetic rats." (PMID 31311594, 2019).
fibrosis (1 paper, 2024). the formation of excess fibrous connective tissue in an organ or tissue in a reparative or reactive process. "In addition, restoring myocardin expression in the hearts of Atp6v0d1AKO mice also reduced cardiomyocyte size and cardiac fibrosis." (PMID 38505620, 2024).
glucose metabolism disorders (1 paper, 2024). "Collectively, these data indicate that FoxO1 mediates myocardin downregulation-induced lipid and glucose metabolism disorders." (PMID 38505620, 2024).
head and neck squamous cell carcinoma (1 paper, 2020). A squamous cell carcinoma that arises from any of the following anatomic sites: lip and oral cavity, nasal cavity, paranasal sinuses, pharynx, larynx, and salivary glands. "The upregulation of long noncoding RNA (lncRNA) myocardin-induced smooth muscle lncRNA, inducer of differentiation (MYOSLID) was associated with the modulation of partial EMT, leading to metastasis and poor prognosis in head and neck squamous cell carcinoma (HNSCC)." (PMID 33207810, 2020).
Holt-Oram syndrome (1 paper, 2011). Holt-Oram syndrome (HOS) is the most common form of heart-hand syndrome and is characterized by skeletal abnormalities of the upper limbs and mild-to-severe congenital cardiac defects. "Here, we show that myocardin directly interacts with Tbx5, a member of the T-box family of transcription factors involved in the Holt-Oram syndrome." (PMID 21897873, 2011). "Our analysis demonstrates that the Tbx5G80R mutation, which leads to the Holt-Oram syndrome in humans, failed to synergize with myocardin to activate cardiac gene expression." (PMID 21897873, 2011).
Hyperinsulinemia (1 paper, 2017). An increased concentration of insulin in the blood. "Myocyte myocardin may be up-regulated by hyperinsulinemia, and in other muscle cell types myocardin is up-regulated by oxidative stress sensitive miR-145." (PMID 29202762, 2017). "However, hyperinsulinemia does up-regulate myocardin in cardiac myoblasts, which additional to modulating hypertrophy could up-regulate caveolins and caveolae." (PMID 29202762, 2017).
Insulin resistance (1 paper, 2024). Increased resistance towards insulin, that is, diminished effectiveness of insulin in reducing blood glucose levels. "However, a causal link between insulin resistance and increased FoxO1 expression following myocardin downregulation in Atp6v0d1AKO mice remains to be established." (PMID 38505620, 2024). "Consistent with the notion that insulin resistance inhibited Akt activity, Akt phosphorylation was decreased in myocardin knockdown cells." (PMID 38505620, 2024). "Moreover, increasing systemic insulin resistance with rosiglitazone restored cardiac myocardin expression and improved cardiac functions in Atp6v0d1AKO mice." (PMID 38505620, 2024). "Therefore, the myocardin-mediated increase in FoxO1 expression is a result of myocardin-induced insulin resistance." (PMID 38505620, 2024). "Furthermore, we identified myocardin downregulation as a key mechanism of cardiac insulin resistance mediated by decreasing IRS-1 expression, highlighting the therapeutic potential of upregulating myocardin activity for lipodystrophy cardiomyopathy and insulin resistance-related HF." (PMID 38505620, 2024). "However, the expression of IRS-2 was not restored by myocardin upregulation, and serum insulin levels suggested that myocardin upregulation may not alter systemic insulin resistance." (PMID 38505620, 2024).
lipodystrophy (1 paper, 2024). A congenital or acquired disorder characterized by abnormal loss or redistribution of the adipose tissue in the body. "Moreover, myocardin serves as a key regulator of cardiac insulin sensitivity and metabolic homeostasis, highlighting myocardin as a potential therapeutic target for treating lipodystrophy- and diabetes-related cardiomyopathy." (PMID 38505620, 2024).
lung adenocarcinoma (1 paper, 2021). A carcinoma that arises from the lung and is characterized by the presence of malignant glandular epithelial cells. "Interestingly, our data suggested that the mRNA expression of MYOCD was dramatically lower in lung adenocarcinoma and squamous carcinoma samples than in paired normal tissues." (PMID 33995678, 2021).
lymphadenitis (1 paper, 2019). Acute or chronic inflammation of one or more lymph nodes. "Validation of gene expression by Taqman quantitative real time PCR confirmed a significantly higher expression of MYOCD mRNA both in MC cHL and NS cHL fibroblasts when compared with lymphadenitis fibroblasts (Mann–Whitney test, p = 0.008 and p = 0.002, respectively)." (PMID 31671543, 2019). "When all cHL fibroblasts (NS cHL and MC cHL fibroblasts) were compared with lymphadenitis fibroblasts, TIMP3 and MYOCD were most strongly and significantly upregulated (4.2- and 3.9-fold, respectively, filter criteria p < 0.05 and FDR < 0.3)." (PMID 31671543, 2019).
mesothelioma (1 paper, 2023). A usually malignant and aggressive neoplasm of the mesothelium which is often associated with exposure to asbestos. "Using transcriptomic data from these models, we identified MEF2C and MYOCD as upstream regulators of the invasive mesothelioma model." (PMID 37146029, 2023).
occlusive vascular diseases (1 paper, 2023). "Hence, we conclude that SMYD2 is a novel regulator of VSMC contractile phenotype and intimal hyperplasia via a myocardin-dependent epigenetic regulatory mechanism and may be a potential therapeutic target for occlusive vascular diseases." (PMID 37090651, 2023).
pancreatic cancer (1 paper, 2011). "In turn, the most commonly deleted gene was MYOCD, a cancer related gene which also displayed LOH in most of our cases (80%); other frequently deleted cancer-associated genes included the EYA3, NR2C1, PTAFR, and the DCC cancer associated genes which have also been involved in pancreatic cancer." (PMID 21811587, 2011).
pleural tumours (1 paper, 2023). "Invasive pleural tumours were characterised by a transcriptomic signature enriched for genes associated with MEF2C and MYOCD signaling, muscle differentiation and myogenesis." (PMID 37146029, 2023).
renal failure (1 paper, 2019). "We observed an increase in MYOCD levels in the endomyocardial biopsies of DCM patients associated with renal failure compared to DCM alone." (PMID 30971740, 2019). "We analyzed the mRNA and protein expression levels of MYOCD in endomyocardial biopsies of DCM patients with and without renal failure." (PMID 30971740, 2019).
type 2 diabetes (1 paper, 2024). "In hearts of high fat diet-induced type 2 diabetes mice, we also found the expression of myocardin, as well as IRS1, was decreased, providing further evidence for this hypothesis." (PMID 38505620, 2024).
urofacial syndrome (1 paper, 2022). "Several monogenic causes of other congenital bladder outflow obstruction disorders have been described including BNC2 in urethral stenosis; FLNA in syndromic urethral anomalies; HPSE2 and LRIG2 in urofacial syndrome; CHRM3 in prune-belly like syndrome; and MYOCD in megabladder." (PMID 36124557, 2022).
viral infection (1 paper, 2018). "Neuronal expression of MHC-1 can be induced by viral infection, however there was no increase in MHC-1 expression within AAV-myocardin shRNA transduced neurons, excluding this possibility." (PMID 29497361, 2018).
cancer (12 papers, 2011 to 2024). A tumor composed of atypical neoplastic, often pleomorphic cells that invade other tissues. "Further to that note, from a large scale analysis of somatic point mutations across 21 human cancer types myocardin was identified as a new oncogene that is mutated in cancer." (PMID 28536630, 2016). "We next asked the molecular mechanisms underlying cancer-stemness suppressive role of MYOCD." (PMID 33995678, 2021). "In addition, influenced by the activation of receptor GALR2, TF MYOCD is upregulated after the signal is transmitted into the nucleus, which causes the development and differentiation of smooth muscle, indirectly promoting the migration of cancer cells." (PMID 35164166, 2022). "SLIT3, ABI3BP, MYOCD, PGM5, TNXB and DNAH9 are strongly associated with cancer initiation and progression." (PMID 36451444, 2022). "Here, we report that expression of MYOCD is downregulated NSCLC cancer samples in comparison to para-tumoral tissues and that its expression is positively correlated with overall survival rate." (PMID 33995678, 2021). "Inactivation of MYOCD could be adaptive response of the NSCLC cancer cells to selection of targeting reagents." (PMID 33995678, 2021).